CTRL (chymotrypsin like)
Diseases named in the same sentence as CTRL in open-access papers:
CTRL is named in the same sentence as 45 diseases in open-access papers, as found by Europe PMC text mining. Sharing a sentence is not in itself a finding about the gene and the disease. The quoted sentences say what the papers report.
COVID-19 (10 papers, 2020 to 2026). A disease caused by infection with severe acute respiratory syndrome coronavirus 2. "The SARS-CoV-2 3-chymotrypsin-like (3CLpro) protease is a key target for the development of COVID-19 therapeutics." (PMID 41957532, 2026). "Several case reports have demonstrated the efficacy of 3-chymotrypsin-like protease inhibitors in treating prolonged coronavirus disease 2019 (COVID-19) in immunocompromised patients." (PMID 39844338, 2025). "A recent international randomized controlled clinical trial showed that the SARS-CoV-2 3-chymotrypsin-like protease (3CLpro) inhibitor PF-07321332 is orally bioavailable and highly effective in reducing the clinical severity of COVID-19." (PMID 35079088, 2022). "Many research teams have exploited the major protease (Mpro) of SARS-CoV-2, also named chymotrypsin-like protease (3CLpr), as a potential drug target to fight COVID-19." (PMID 35423848, 2021). "The prime anti-COVID-19 target proposed is the main protease (Mpro; also known as 3 chymotrypsin like protease or 3CLpro), which is regarded as responsible for the cleavage of viral peptides into functional units for virus replication and packaging within the host cells." (PMID 35423848, 2021). "Among them, glycyrrhizin and glycyrrhetinic acid interact with ACE 2, spike protein, host transmembrane serine protease 2 and 3-chymotrypsin-like cysteine protease to alleviate the common symptoms of COVID-19 patients, such as pulmonary inflammation and liver and kidney injury." (PMID 34899289, 2021). "Ensitrelvir is a novel COVID-19 therapeutic that accelerates viral clearance through inhibition of the main protease of SARS-CoV-2, 3-chymotrypsin-like protease, which is vital for viral replication." (PMID 38333218, 2024).
breast carcinoma (2 papers, 2021 to 2024). "We also found two transcription factors (ROCK2, USF3) in the distal components of the CTRL- and MAP3K6-associations with survival; both transcription factors are interconnected within the MAPK pathway, known to be involved in breast cancer proliferation." (PMID 33684137, 2021).
cardiac hypertrophy (2 papers, 2020 to 2021). "Our results showed that the administration of PR-957 specifically reduced chymotrypsin-like activity and blocked PTEN degradation, resulting in the prevention of hypertrophic remodeling including cardiac hypertrophy, fibrosis, and inflammation in mice after 2-week Ang II infusion." (PMID 32595507, 2020). "PRL treatment induced cardiac dilatation and cardiac hypertrophy in CM-KO but not in CTRL mice." (PMID 34548576, 2021).
glioma (2 papers, 2023 to 2025). A benign or malignant brain and spinal cord tumor that arises from glial cells (astrocytes, oligodendrocytes, ependymal cells). "Here, we present evidence that the dual inhibition of LonP1 and Chymotrypsin-like (CT-L) proteasome activity effectively induces cellular reactive oxygen species (ROS) production, leading to apoptosis in malignant astrocytoma established cell lines and patient-derived glioma stem cell-like cultures." (PMID 40088962, 2025). "We identified 8 plasma proteins which were increased in gliomas vs. meningiomas (GFAP, NEFL, EDDM3B, PROK1, MMP3, CTRL, GP2, SPINT3) and 4 proteins which were decreased in gliomas vs. meningiomas (FABP4, ALDH3A1, IL-12B and OXT)." (PMID 36959545, 2023). "For the other identified candidate biomarkers (EDDM3B, LMOD1, GP2, SPINT3, CTRL, OXT) there is no specific literature linking them to gliomas or other brain tumors." (PMID 36959545, 2023).
malignant melanoma (2 papers, 2020 to 2024). "The aim of our study was to verify the ability of marizomib—a natural inhibitor that inhibits all three proteasome activities (caspase-like (C-L, β1), trypsin-like (T-L, β2), and chymotrypsin-like (CT-L, β5))—to induce cellular senescence in two malignant melanoma lines: A375 and G361." (PMID 39683813, 2024).
ovarian carcinoma (2 papers, 2016 to 2017). A malignant neoplasm originating from the surface ovarian epithelium. "Our results further confirmed that Lewis y antigen may promote the proliferation and survival of ovarian cancer cells by increasing intracellular chymotrypsin-like proteasome activity." (PMID 29299130, 2017).
pancreatic cancer (2 papers, 2018 to 2023). "We validated the expression level of COL11A1, GJB2 and CTRL with IHC assay of 46 paired pancreatic cancer and para-cancerous tissue sections." (PMID 30410422, 2018). "The result showed that high expression level of COL11A1, GJB2 or low expression level of CTRL in pancreatic cancer tissue sections indicated poorer prognosis and less survival rate." (PMID 30410422, 2018). "Results of bioinformatic analysis and IHC analysis suggested that COL11A1, GJB2 and CTRL are novel predictive biomarkers for pancreatic cancer." (PMID 30410422, 2018). "Furthermore, no published paper evaluated the expression and predictive value of COL11A1, GJB2 and CTRL in pancreatic cancer." (PMID 30410422, 2018). "COL11A1, GJB2 and CTRL are novel predictive biomarkers for pancreatic cancer." (PMID 30410422, 2018). "Finally, we selected and validated the clinical predictive value of COL11A1 (collagen alpha-1(XI) chain), GJB2 (gap junction beta-2 protein) and CTRL (chymotrypsin-like protease CTRL-1) with immunohistochemical (IHC) analysis of 46 paired pancreatic cancer and para-cancerous tissue sections." (PMID 30410422, 2018).
schizophrenia (2 papers, 2019 to 2021). A major psychotic disorder characterized by abnormalities in the perception or expression of reality. "The AM module, which was most enriched for MIA + CTRL microglia, showed enrichment for synaptic molecules, FMRP-, schizophrenia-, and ASD-implicated genes, while the MIA-IM cluster showed enrichment for genes with de novo mutations identified in human ASD and “M2” ASD prenatal genes." (PMID 32071385, 2021).
acute pancreatitis (1 paper, 2020). An acute inflammatory process that leads to necrosis of the pancreatic parenchyma. "Still, the CTRL-dependent changes in intrapancreatic protease activation did not have a significant impact on the severity of cerulein-induced acute pancreatitis." (PMID 32678161, 2020).
Anxiety (1 paper, 2018). Intense feelings of nervousness, tension, or panic often arise in response to interpersonal stresses. "Tg CTRL mice demonstrated increased locomotor activity and decreased anxiety‐like behavior in comparison with WT CTRL mice." (PMID 30079520, 2018).
autoimmune disease (1 paper, 2015). A disorder resulting from loss of function or tissue destruction of an organ or multiple organs, arising from humoral or cellular immune responses of the individual to their own tissue constituents. "Thus, multiple ncRNA species exhibit increased polyadenylation in RRMS relative to CTRL or other autoimmune diseases." (PMID 25885816, 2015).
Brain atrophy (1 paper, 2018). Partial or complete wasting (loss) of brain tissue that was once present. "Taken together, Tg CTRL mice had increased BBB leakage and larger ventricles volumes, compared to Tg HFD mice suggesting that HFD protected against BBB disruption and brain atrophy in AD‐like mice." (PMID 30079520, 2018).
brain injury (1 paper, 2015). Acute and chronic (see also brain INJURIES, CHRONIC) injuries to the brain, including the cerebral hemispheres, CEREBELLUM, and brain STEM. "Since NF-κB signaling is associated with activation of the proteasome, which is one key component in developing ischemic brain injury, chymotrypsin-like activity was measured in brain lysates." (PMID 26050199, 2015).
chronic pancreatitis (1 paper, 2020). A chronic inflammatory process causing damage and fibrosis of the pancreatic parenchyma. "The potential link of variants in the human CTRL gene and chronic pancreatitis has not been investigated so far." (PMID 32678161, 2020).
colitis (1 paper, 2021). Inflammation of the colon. "Chymotrypsin-like, cathepsin G, elastase-like, and kallikrein activities were comparable in post-colitis and control animals." (PMID 34072320, 2021).
Constipation (1 paper, 2024). Infrequent or difficult evacuation of feces. "The present results suggest that C3 deficiency-induced constipation may be associated with 1237 upregulated genes including PNLIP, CEL, CPB1, CTRL, PNLIPRP1, and REG1 as well as 1292 downregulated genes including Eif2s3y, UTY, KDM5D, IGKV6-32, Olfr870, and DDX3Y." (PMID 39273477, 2024).
Crohn disease (1 paper, 2021). A gastrointestinal disorder characterized by chronic inflammation involving all layers of the intestinal wall, noncaseating granulomas affecting the intestinal wall and regional lymph nodes, and transmural fibrosis. "While LMP2 caspase-like activity was reduced both in IBS and Crohn’s disease patients, trypsin-like (MECL1) activity was increased more in IBS compared to Crohn’s disease and control patient samples, and the chymotrypsin-like activity (LMP7) was upregulated in Crohn’s disease patients only." (PMID 34356615, 2021).
exocrine pancreatic insufficiency (1 paper, 2023). Inability of the exocrine pancreas to produce and secrete an adequate amount of digestive enzymes into the small intestine. "Within those proteins more abundant in DHD and CHD than HD, Chymotrypsin-like elastase has been associated with exocrine pancreatic insufficiency in man; therefore, it is difficult to contextualize herein." (PMID 37508119, 2023).
pancreatitis (1 paper, 2020). Inflammation of the pancreas. "To this end, we generated a novel CTRL-deficient mouse strain (Ctrl-KO) and evaluated intrapancreatic protease activation and the severity of pancreatitis caused by cerulein injections." (PMID 32678161, 2020). "Nonetheless, the present study clearly indicates that CTRL is a minor chymotrypsin isoform in mice that is relatively unimportant for pancreatitis." (PMID 32678161, 2020). "In the present study, we set out to determine the significance of CTRL in experimental pancreatitis of mice." (PMID 32678161, 2020). "Taken together, the observations demonstrate the biochemical basis of a potential protective effect of CTRL against pancreatitis." (PMID 32678161, 2020). "Here we investigated the role of CTRL in cerulein-induced pancreatitis in mice." (PMID 32678161, 2020). "In the present study we investigated the role of CTRL in cerulein-induced pancreatitis in mice." (PMID 32678161, 2020). "The role of CTRL in pancreatitis, however, has remained unclear." (PMID 32678161, 2020). "In contrast to the demonstrated protective effects of CTRB1 and CTRC in mice against pancreatitis, the observations reported here did not indicate a similar role for CTRL." (PMID 32678161, 2020). "We conclude that CTRL is a minor chymotrypsin isoform that plays no significant role in cerulein-induced pancreatitis in mice." (PMID 32678161, 2020). "Therefore, CTRL does not play a significant role in secretagogue-induced pancreatitis in mice." (PMID 32678161, 2020).
rheumatoid arthritis (1 paper, 2025). A chronic, systemic autoimmune disorder characterized by inflammation in the synovial membranes and articular surfaces. "Elevated trypsin-like serine proteinase levels were observed in the synovial fluid (SF) of PsA and rheumatoid arthritis (RA) patients compared to those with osteoarthritis (OA), whereas chymotrypsin-like activity was higher in RA than in PsA." (PMID 40430897, 2025).
status epilepticus (1 paper, 2017). Status epilepticus is defined as a continuous seizure lasting more than 30 min, or two or more seizures without full recovery of consciousness between any of them. "We then subjected wild-type mice to KA-induced status epilepticus and measured chymotrypsin-like proteasome activity in all different hippocampal subfields at different time-points post KA injection." (PMID 28235423, 2017).
tumor (19 papers, 2007 to 2025). "The human kallikrein family comprises 15 homologous, single-chain, secreted trypsin- or chymotrypsin-like serine proteases (KLK1–15) and has been implicated in regulation of tumor growth, neoplastic progression, angiogenesis and metastasis." (PMID 32993568, 2020). "The intracellular chymotrypsin-like proteasome activity has been proven to be closely related to the state of tumor cells." (PMID 29299130, 2017). "This evaluation detected CELA1 and CTRL primarily in tumor cells, although expression was detected in normal epithelial cells." (PMID 27081040, 2016). "Galectin-3 is a tumor-associated protein; present in the seminal fluid and is a substrate for the PSA enzyme e.g., a chymotrypsin-like serine protease." (PMID 23625538, 2013). "Caspase-like and chymotrypsin-like activities from monolayers increased over 2 hours of incubation with substrates, but remained unchanged in tumor sphere lysates." (PMID 20949018, 2010). "Plasma kallikrein, a component of the human kallikrein-related peptidases has been found to have aberrant abundance in multiple cancer types, including GI cancers, which affects the cascade of tumor management, such as trypsin and chymotrypsin-like serine peptidases." (PMID 40559996, 2025). "This protein is a chymotrypsin-like serine protease that is abundantly expressed in innate effector natural killer cells and acts as a first line of defence against virus-infected or transformed tumour cells." (PMID 34781893, 2021). "Likewise, all tumor growth was abrogated in IT treated CD4+ CTRL and CD4 KO mice whereas most tumors displayed progressive outgrowth in vehicle treated mice." (PMID 25119341, 2014). "Our data could be explained by a dilution of genes expressed from tumor cells infiltrating the BAT samples: in fact the genes overexpressed in BAT against CTRL were also over-expressed in GBM but with a higher fold change." (PMID 23472076, 2013). "We subcutaneously injected BC cells into nude mice to establish xenograft tumor models and treated the mice with LNP-si-MNX1-AS1 or LNP-si-CTRL." (PMID 40520020, 2025). "However, the number of metastasis did not correlate with survival time for CTRL siRNA‐treated tumours (data not shown) indicating that lung nodule formation is not the cause of mouse death in this mouse model which is instead due to extensive haemorrhage from ulceration of tumours." (PMID 29044946, 2018). "Moreover, in tumor tissues, CELA1 and CTRL were detected in both tumor and stromal cells, and the levels of the two proteases were significantly increased in the tumor cells not in stromal cells." (PMID 27081040, 2016).
infection (9 papers, 2014 to 2023). The state of being infected such as from the introduction of a foreign agent such as serum, vaccine, antigenic substance or organism. "When CF cells were treated with Myr (MyrAspCF), the number of common regulated genes increased up to 439, indicating that Myr drives CF response to infection and partially restores the CTRL expression profile." (PMID 32781626, 2020). "Upon infection of the TRIM22-KD and CTRL-KD SupT1 cells with the different HIV-rtTA variants, virus replication was followed up to 32 days post-infection (PI)." (PMID 26683615, 2015). "This revealed that, at 6 and 12 h post-infection, both vectors reduced the trypsin-like activity, as compared to uninfected cells, whereas the chymotrypsin-like activity was comparable to that of untreated cells." (PMID 25033084, 2014). "Interruption of cellular translation during infection can also be mediated by FMDV 3Cpro, a chymotrypsin-like cysteine protease that similarly to Lpro targets eIF4G and the cap-binding complex eIF4A for cleavage, although these events occur later in the infection." (PMID 32851039, 2020). "Importantly, a higher MOI was generally required for infection of cells with constitutive overexpression of CTRL or TRIM16, perhaps as a result of their different culture conditions (i.e., in the presence of hygromycin) when compared to cells with DOX-inducible overexpression." (PMID 37375542, 2023). "As expected based on ASFV growth kinetics, the most profound changes were observed at 8 h after infection, whereas at later stages of infection, the levels of viral proteins in VPS39-KO cells stabilized and were comparable with those observed in CTRL-KO cells." (PMID 36722971, 2023). "Targeting the structural proteins or cellular receptors of 2019-nCoV, including coronavirus chymotrypsin-like (3CLpro or Mpro), helicase (nsP13), S protein, and human angiotensin converting enzyme 2 (ACE2), holds promise for preventing infection." (PMID 32719799, 2020).
cancer (7 papers, 2008 to 2025). A tumor composed of atypical neoplastic, often pleomorphic cells that invade other tissues. "Chymotrypsin-like proteasome activities are inhibited by systemic exposure with chemotherapeutics in anti-cancer therapy, which primarily affects subunits β5, Lmp2 and Lmp7 in the heart." (PMID 38516190, 2024). "In cancer treatment an attempt has been made to pharmacologically regulate the proteasome functions, thus the aim was to test whether 20S proteasome chymotrypsin-like (ChT-L) activity has a role in glial brain tumors." (PMID 32886667, 2020). "Although we demonstrated that our micelles can be recognized by the proteolytic enzyme chymotrypsin, which is an enzyme expressed in the pancreas for digestion of hydrophobic peptides, it is important to note that chymotrypsin-like enzymes are widely overexpressed in human cancers." (PMID 31075929, 2019). "The relationship between GJB2, CTRL and cancer progression was not reported." (PMID 30410422, 2018).
cardiovascular diseases (1 paper, 2023). "Overall, our results show that M. aitchisonii produces an acid-tolerant and antioxidative chymotrypsin-like fibrinolytic enzyme, and M. aitchisonii containing MA-1 could be a beneficial functional material for the prevention of cardiovascular diseases and possible complications." (PMID 37627553, 2023).
myopathy (1 paper, 2013). A disease of the muscle in which the muscle fibers do not function properly. "In GNE myopathy biopsies, chymotrypsin-like (CTL), trypsin-like (TL), and peptidyl-glutamyl peptide-hydrolyzing (PGPH) protease activities were increased by 48.2%, 55.3%, and 27.5% (P<0.05), respectively compared with the control biopsies." (PMID 23472144, 2013).
CTRL also shares sentences with these, for which no sentence is quoted: Arthritis (1 paper); bacterial infections (1); brain tumors (1); epilepsy (1); frontotemporal lobar degeneration (1); hepatoma (1); Hyperglycemia (1); Immunodeficiency (1); intestinal lymphangiectasia (1); leukaemia (1); lymphoma (1); malignant astrocytoma (1); meningioma (1); mesothelioma (1); multiple myeloma (1); oropharyngeal squamous cell carcinoma (1); prediabetes (1); progressive supranuclear palsy (1); Sepsis (1).